G6PD (glucose-6-phosphate dehydrogenase)
Diseases named in the same sentence as G6PD in open-access papers (continued):
Sharing a sentence is not in itself a finding about the gene and the disease.
G6PD deficiency (continued). "Glucose-6-phosphate dehydrogenase (G6PD) enzyme function and genotype were determined in Ugandan children with uncomplicated falciparum malaria enrolled in a primaquine trial after exclusion of severe G6PD deficiency by fluorescent spot test." (PMID 24913169, 2014). "The observation that some G6PD-deficient individuals were FST normal is unsurprising since the test may be insufficiently sensitive to detect mild G6PD deficiency, but there are few supportive published data." (PMID 24913169, 2014). "The distribution of thalassemia frequency was similar to the situation of G6PD deficiency in Jiangxi province, further confirmed the hypothesis that both human G6PD and the β-globin gene were involved in malaria-protective selection." (PMID 25000193, 2014). "Among the two major ethnic groups, Burmans showed greater diversity of G6PD deficiency mutations compared to Karen; among the 16 deficient subjects of Burman origin 10 had the Mahidol variant while among the 50 G6PD deficient subjects of Karen ancestry, 49 had Mahidol variant (P<0.01)." (PMID 25536053, 2014). "Glucose-6-phosphate dehydrogenase (G6PD) deficiency is a common inherited enzyme defect and an important problem in areas with Plasmodium vivax infection because of the risk of haemolysis following administration of primaquine to treat the liver forms of the parasite." (PMID 24586352, 2014). "The comparable hematocrits between G6PD deficient and sufficient individuals in our sample supports the finding that clinically evident chronic hemolysis is a relatively rare feature of African G6PD deficiency." (PMID 23874768, 2013). "In most regions with high G6PD prevalence several polymorphic alleles are in circulation with the notable exception of sub-Saharan Africa where A is thought to cause 90% or more of G6PD deficiency." (PMID 23537118, 2013). "Given the risk of haemolysis in G6PD deficient individuals, and the genetic and phenotypic variability of G6PD deficiency across geographic areas where primaquine treatment is considered, estimation of G6PD enzyme function prior to drug administration is recommended." (PMID 23782846, 2013). "Jaundice is a common disorder in neonates and one of the provable causes of glucose-6-phosphate dehydrogenase (G6PD) deficiency, some mutation types of which may be associated with severe neonatal icter." (PMID 24551785, 2013). "The lower haemoglobin levels in children with normal G6PD in this study may be attributable to G6PD deficiency being associated with a protective effect against infections that may result in anaemia, however, the study was not powered to test this effect." (PMID 23782846, 2013). "Analysis of 937 blood samples for G6PD deficiency revealed two subjects (0.2%) of deficient G6PD." (PMID 22908898, 2012). "Measurement of the prevalence of glucose-6-phosphate dehydrogenase (G6PD) deficiency using a colorimetric assay identified 0.8% subjects with less G6PD activity, and molecular analyses found Vianchang type G6PD deficiency mutation (Syafruddin, unpublished report)." (PMID 22908898, 2012). "The degree of G6PD deficiency is an individual characteristic of each G6PD variant." (PMID 23237606, 2012). "For example, one patient was heterozygous for glucose-6-phosphate dehydrogenase (G6PD) deficiency." (PMID 22462806, 2012). "It is, therefore, contraindicated in patients with G6PD deficiency and pregnancy (due to the unknown G6PD status of the foetus)." (PMID 22727113, 2012). "In this study, we determined G6PD enzyme levels and sequenced the coding region, including the intron-exon boundaries, in a group of individuals (163 males and 86 females) who were referred to the clinic with suspected G6PD deficiency." (PMID 23006493, 2012). "However, primaquine and tafenoquine cause predictable, intravascular haemolysis in individuals with glucose-6-phosphate dehydrogenase (G6PD) deficiency." (PMID 22164279, 2011).
G6PD deficiency (continued). "G6PD deficiency prevalence was 9.0% (184/2045; 7.2% [N = 147] male hemizygous plus 1.8% [N = 37] female homozygous), 13.3% (273/2045) of patients were heterozygous females, 77.7% (1588/2045) were G6PD normal." (PMID 21849081, 2011). "Dapsone can produce dose-related haemolysis that can be severe in patients with G6PD deficiency, but data about the toxic dose in G6PD deficient subjects were limited, (based primarily on data from 5 G6PD deficient male inmates of Illinois State penitentiary given daily doses over 21 days)." (PMID 21666744, 2011). "They measured G6PD activity in the participants' blood to detect “phenotypic” G6PD deficiency (reduced enzyme activity) and looked for the Mediterranean variant of the G6PD gene in the participants (“genotypic” G6PD deficiency)." (PMID 20520804, 2010). "The clearance of P. falciparum using ACT in G6PD-deficient patients with uncomplicated malaria may require both enzymatic assay and genetic analysis of the mutation to detect and characterize G6PD deficiency." (PMID 21092137, 2010). "Within the haemoglobinuria group of those patients with measured G6PD deficiency 39.6% (19/48) harboured non-synonymous G6PD polymorphisms, and 14/48 had a synonymous polymorphism (9/48 of these patients harboured both synonymous and non-synonymous G6PD polymorphisms)." (PMID 19589177, 2009). "G6PD mutations were screened in patients with haemoglobinuria and in G6PD deficient healthy individuals to identify the G6PD variants causing G6PD deficiency in the Vietnamese general population and to investigate the contribution of G6PD mutations to the development of haemoglobinuria." (PMID 19589177, 2009). "Phenotypic screening for G6PD deficiency in healthy individuals from two ethnic groups, the Vietnamese Kinh and S'tieng, showed that the overall prevalence of the G6PD deficient phenotype in the southern Vietnamese population is relatively high at 11.3% (59/524)." (PMID 19589177, 2009). "Only one variant was a borderline class 2 or 3 G6PD deficiency (G6PD Frankfurt)." (PMID 17637841, 2007). "However, due to the serious toxicity (hemolysis) that can occur in patients with glucose-6-phosphate dehydrogenase (G6PD) deficiency, the patient’s G6PD status would need to be assessed before treatment with a CQ–PQ combination." (PMID 17661691, 2006). "The findings from this study show that MB appears to be safe at an oral dose of up to 4 mg/kg/day over three days in SSA populations with dominating class III G6PD deficiency, despite its being on the list of drugs reported to potentially cause severe haemolysis in G6PD-deficient populations." (PMID 16179085, 2005). "In addition, in women with glucose-6-phosphate dehydrogenase (G6PD) deficiency, it may lead to severe hemolytic anemia." (PMID 41597317, 2025). "Advancements in G6PD screening and genetic testing programs in both high-income and low-to-middle-income countries have significantly increased the global recognition and diagnosis of G6PD deficiency, underscoring the necessity for updated surveillance and management strategies worldwide." (PMID 40486677, 2025). "Indeed, given the ubiquity of G6PD in immunologically-relevant pathways and processes, it is clear that more research is needed to improve our understanding of the immunologic role of G6PD and G6PD deficiency in health and disease." (PMID 38938571, 2024). "Our study demonstrates that this model of routine G6PD screening and routine follow-up could reduce the need for exchange transfusion and help prevent chronic sequelae of hyperbilirubinemia associated with G6PD deficiency." (PMID 38480787, 2024). "Thus, G6PD activity at baseline (day 1) could be used as reference value for ruling out G6PD deficiency and initiating primaquine treatment early during P. vivax infection." (PMID 38725027, 2024). "Furthermore, a repeat G6PD screen post-discharge confirmed the diagnosis of G6PD deficiency." (PMID 39170996, 2024).
G6PD deficiency (continued). "It is important to emphasize that in G6PD deficiency, various mutations in the same codon have been reported where the native amino acid residue was changed by different amino acid residues, producing different G6PD variants that have been reported in different countries around the world." (PMID 39684266, 2024). "In addition, testing for Glucose-6-Phosphate Dehydrogenase (G6PD) deficiency to safely administer the radical cure for P. vivax cases, which have contributed 90% of malaria burden in Cambodia since 2020, provides an opportunity for VMWs to fill in the gap in community case referral." (PMID 39661587, 2024). "For example, in G6PD-deficient individuals, residual hepatic enzyme activity can prove insufficient in stress states where increased G6PD activity is required, as in neonates with comorbid G6PD deficiency and Gilbert’s syndrome, who are at increased risk for hyperbilirubinemia." (PMID 38938571, 2024). "However, the primary issue with TQ-based eradication campaigns remains the contraindication of 8-AQs for those with glucose-6-phosphate dehydrogenase (G6PD) deficiency or unknown G6PD status." (PMID 38640243, 2024). "Furthermore, the incidence of G6PD-deficient individuals with SARS-CoV-2 infections should also be calculated; the viral load could also be compared between patients with wild-type G6PD and G6PD deficiency." (PMID 36905446, 2023). "G6PD deficiency was found to be more prevalent in infected males and suggested to be a predictor of hospitalization and severe infections and consequently higher mortality rates probably due to the association between sex-linked gene and G6PD leading to predominance of more severe disease in males." (PMID 36978361, 2023). "Future operational studies should investigate whether testing strategies that involve repeat testing over two or three consecutive occasions can improve confirmation of true G6PD deficient cases and the effective positive predictive value specially in settings with low prevalence in G6PD deficiency." (PMID 37824592, 2023). "G6PD deficiency is one of the most common enzymopathies with more than 400 million individuals affected worldwide, mostly men; it is an X-linked recessive genetic disorder characterized by the markedly reduced enzymatic activity of G6PD as a result of defective production." (PMID 36905446, 2023). "However, it is important to note that this only applies to patients with less severe forms of G6PD deficiency; in severe class I G6PD deficiencies, G6PD levels may be too low to even adequately clear viral infections." (PMID 36905446, 2023). "G6PD deficiency is classified as an X-linked recessive inborn error that primarily affects males, while heterozygous females may exhibit normal, intermediate, or deficient G6PD activity due to random X chromosome inactivation." (PMID 38264207, 2023). "Therefore, the purposes of this study were to assess the effect of reticulocytosis in the determination of blood G6PD activity in Thai newborns by using a novel automated UV-based enzymatic assay and to validate the performance of this assay for the detection of G6PD deficiency in newborn samples." (PMID 36419023, 2022). "Hyperglycemia may offset the effects of G6PD deficiency by increasing the production of G6PD." (PMID 35402109, 2022). "Therefore, this study could be confirmed with the evidence of the prevalence of G6PD deficiency in the southern Thai population, and G6PD-Viangchan and G6PD-Mahidol are the two most common G6PD mutations, consistent with previous reports." (PMID 36248708, 2022). "New point-of-care (POC) quantitative G6PD testing devices developed to provide safe radical cure for Plasmodium vivax malaria may be used to diagnose G6PD deficiency in newborns at risk of severe neonatal hyperbilirubinaemia, improving clinical care, and preventing related morbidity and mortality." (PMID 36523222, 2022).
G6PD deficiency (continued). "Although, the prevalence of G6PD deficiency in females (9.1%) in this population was higher than that reported previously (5.3%), as a result of the small number of the female patients, the frequency of G6PD mutation in females follows Hardy–Weinberg equilibrium." (PMID 36038921, 2022). "In addition, medication nephrotoxicity may be impacted by disease- and/or individual- related risk factors as well as population genetics (e.g., glucose-6-phosphate dehydrogenase (G6PD) deficiency)." (PMID 35198918, 2022). "Subsequently, COVID-19 studies on hospitalized patients with G6PD deficiency have shown that they require more oxygen supplementation and more prolonged mechanical ventilation support, indicating an increased severity of pneumonia, than G6PD wild-type patients." (PMID 35880537, 2022). "Importantly, when observing increased levels of G6PD activity, thresholds for definition of “G6PD deficiency” increased proportionally; should adult thresholds be applied to infants, deficient and intermediate infants would be inappropriately classified as normal." (PMID 38406309, 2022). "Available evidence shows that the WHO-recommended SLD primaquine dose added to effective schizonticides is safe and well-tolerated even in individuals with G6PD deficiency, and therefore, it may safely be used in the African population with the mildest G6PD A- variant." (PMID 35216617, 2022). "The variations observed in the distribution of G6PD variants are most likely due to the very low prevalence of G6PD deficiency amongst the people in Asutsuare, which could suggest that the prevalence of G6PD deficient (G6PDd) variants decreased with decreasing transmission intensity." (PMID 35291755, 2022). "In addition, reticulocytosis in carriers of double defect (beta-thalassemia + G6PD deficiency) may increase the G6PD activity above the threshold, and deficient subjects may be falsely classified as normal." (PMID 34007401, 2021). "To characterise the possible protective effects of G6PD Med against P. vivax malaria, we conducted a retrospective analysis of case–control data from clinical studies on vivax malaria, and epidemiological studies of G6PD deficiency that we have conducted in Afghanistan over the past 10 years." (PMID 33543710, 2021). "Thus, the prevalence of G6PD deficiency in males is equivalent between these two assays, but in females, genetic analysis using HRM indicated a high frequency of g6pd gene mutations (34.45 %), that is notably greater than the prevalence of G6PD deficiency measured by WST-8 (21.01 %)." (PMID 33879156, 2021). "Patients with G6PD deficiency may be more vulnerable to severe acute respiratory syndrome coronavirus 2 (SARS-CoV-2) infection as G6PD-deficient lung cells infected with human coronavirus 229E result in increased viral production and replication compared with normal cells." (PMID 34178542, 2021). "Although primaquine is routinely prescribed with chloroquine to suppress P. vivax relapses in Latin America, infants <6 months of age with unknown glucose-6-phosphate dehydrogenase (G6PD) deficiency status are considered primaquine-ineligible in Brazil because of the risk of hemolysis." (PMID 34264946, 2021). "Thus, our observations, combined with the appreciation of the high penetration of G6PD deficiency in human populations, raise the possibility of a previously unappreciated role for G6PD status and biology in solid tumors, analogous to what has been proposed for hematological malignancies." (PMID 34138756, 2021). "As with eucalyptus oil, the results from zebrafish with G6PD deficiency exposed to methylated spirits also show a higher rate of hemolysis, suggesting, like eucalyptus, these spirits may be a concern for neonates with G6PD deficiency." (PMID 33154437, 2020).
G6PD deficiency (continued). "Finally, G6PD A- mice had higher mean glucose levels compared to WT littermates, consistent with clinical studies demonstrating increased incidence of diabetes mellitus and/or impaired fasting glucose in patients with G6PD deficiency." (PMID 33007039, 2020). "However, in people with sickle cell disease (SCD), sickle cell trait (SCT), α-thalassemia or glucose-6-phosphate dehydrogenase (G6PD) deficiency, HbA1c may underestimate the prevalence of diabetes." (PMID 33382828, 2020). "We thus hypothesized that G6PD deficiency increases the risk of pneumococcal bacteremia in African children and that this effect is dependent on intense malaria transmission resulting in severe anemia among G6PD-deficient children." (PMID 32536341, 2020). "However, since 1992, G6PD-deficient clinical cases have been continuously reported at domestic hospitals, possibly as a consequence of increased immigration from Southeast Asia, where G6PD deficiency prevalence is relatively high." (PMID 32873296, 2020). "Further genotyping studies are needed to confirm the presence of additional variants that may be associated with G6PD deficiency and determine further the frequencies of mutations in G6PD in the general population as well as in different ethnic groups in relation to P. vivax infection." (PMID 31525211, 2019). "Similarly, a robust G6PD newborn screening program paired with health education programs implemented in the Sassari district of Sardinia, Italy, was associated with a 75% decline in clinical complications associated with G6PD deficiency." (PMID 31709308, 2018). "A latent deficiency of G6PD may become clinically manifest under the appropriate triggering conditions even in elderly patients and in the absence of past or current clinical and laboratory evidence of G6PD deficiency." (PMID 30356359, 2018). "Thus, asymptomatic individuals often remain unaware of their G6PD genotype status and screening for the G6PD genotype before using HbA1c to diagnose T2D may be warranted in populations or ethnic groups where G6PD deficiency is common." (PMID 28898252, 2017). "More than 160 G6PD genetic variants have been identified including G6PD B (wild type), G6PD A (non-deficient type) and G6PD A− (African deficient type); however the most common and more frequently associated with G6PD deficiency in sub Saharan Africa is the 376G/202A haplotype." (PMID 28793894, 2017). "Genotypes were obtained at four nonsynonymous polymorphic loci within G6PD known to be associated with enzyme deficiency, including A968G, T542A, C680A, and C202T, in order to comprehensively survey the genetic diversity underlying G6PD deficiency in West Africa." (PMID 26738565, 2016). "The overall prevalence of G6PD deficiency was 13 % [36/278; 3 % (4/132) female homozygous and 22 % (32/146) male hemizygous], 14 % (40/278) children were female heterozygous while 73 % (202/278) were G6PD normal [67 % (88/132) females and 78 % (114/146) males] individuals." (PMID 27388012, 2016). "Interestingly, detectable parasitaemia was significantly less prevalent in individuals with severe or intermediate G6PD deficiency (OR = 0.44), and overall the risk of moderate anaemia was significantly higher in G6PD normal individuals (OR = 6.7 [1.6–28]; p = 0.001)." (PMID 27788243, 2016). "Finally, the Class III G6PD A+ variant shows an A → G substitution in the exon at nt 376 with a change in the 126 (Asn → Asp) amino acid residue and is related to an asymptomatic G6PD deficiency form." (PMID 26633385, 2015). "However, despite a fairly large sample, the study was underpowered to determine whether the adverse effects of CD are exacerbated among infants with G6PD deficiency, primarily because these deficient G6PD genotypes were uncommon." (PMID 26599634, 2015). "However, because primaquine can induce haemolytic anaemia in persons affected by G6PD deficiency, it is contraindicated in pregnant women given the unknown neonatal G6PD status." (PMID 24758193, 2014).